ERAP1 (endoplasmic reticulum aminopeptidase 1)
Diseases named in the same sentence as ERAP1 in open-access papers (continued):
Sharing a sentence is not in itself a finding about the gene and the disease.
colitis (3 papers, 2018 to 2025). Inflammation of the colon. "ERAP1+/− mice on a C57BL/6 background were generated to assess the effects of partial ERAP1 expression on colitis susceptibility." (PMID 40977735, 2025). "ERAP1+/- mice exhibited mildly increased susceptibility to DSS-induced colitis, with greater weight loss and distinct alterations in immune cell infiltration compared to WT mice." (PMID 40977735, 2025). "A previous study showed that ERAP1-deficient mice exhibit increased susceptibility to DSS-induced colitis, characterized by extensive ulceration and colonic irritation." (PMID 40977735, 2025). "Recent studies have highlighted the role of ERAP1 in the progression of colitis and response to sulfasalazine, using a colitis-susceptible ERAP1 heterozygous (ERAP1+/−) mouse model." (PMID 40977735, 2025). "ERAP1+/− mice showed mildly increased susceptibility to DSS-induced colitis, evidenced by greater weight loss and altered expression of immune cell markers, including those of neutrophils, DCs, T cells, and NK cells even after sulfasalazine treatment." (PMID 40977735, 2025). "ERAP1+/− colitis mice showed mildly increased susceptibility to colitis, along with distinct changes in immune cell infiltration and gene expression profiles." (PMID 40977735, 2025). "This study aimed to investigate the role of ERAP1 in the response to sulfasalazine, a standard treatment for UC, using an ERAP1-heterozygous (ERAP1+/-) mouse model susceptible to colitis." (PMID 40977735, 2025). "ERAP1 knockout mice (ERAP1−/−) show increased susceptibility to DSS-induced colitis, potentially driven by alterations in the gut microbiota, although the precise molecular mechanisms remain poorly understood." (PMID 40977735, 2025). "ERAP1 is also known to cause shedding of IL-6, further linking ERAP1 and regulation of IL-6 in colitis." (PMID 35246034, 2022). "Elucidating the mechanistic basis of ERAP1 deficiency in colitis pathogenesis could provide novel insights for developing therapeutic strategies for IBD." (PMID 40977735, 2025). "Moreover, ERAP1+/− mice exhibited a 70% increase in Ly6G+CD11b+ neutrophil levels compared to WT mice under colitis conditions, indicating that partial ERAP1 deficiency affects neutrophil infiltration in this model." (PMID 40977735, 2025). "Lastly, our flow cytometry analyses focused on selected immune subsets; broader profiling, including Tregs and innate lymphoid cells, may offer a more comprehensive view of the immune landscape in ERAP1-associated colitis." (PMID 40977735, 2025). "Previously, we demonstrated that ERAP1−/− mice have enhanced susceptibility to DSS-induced colitis." (PMID 35246034, 2022). "First, although ERAP1+/− mice showed heightened colitis severity and altered immune cell profiles, the precise molecular mechanisms by which partial ERAP1 deficiency influences specific immune pathways (e.g., neutrophil activation, DC maturation, CD4+ T cell function) remain unclear." (PMID 40977735, 2025). "Anxa9, a novel marker associated with poor prognosis, was significantly upregulated in ERAP1+/− colitis mice compared to ERAP1+/− controls (p < 0.05), with a further significant increase observed following sulfasalazine treatment (p < 0.05)." (PMID 40977735, 2025). "In contrast, CD86+ cells were significantly reduced in ERAP1+/− colitis mice (p < 0.05); this reduction was also observed following sulfasalazine treatment (p < 0.05)." (PMID 40977735, 2025). "Notably, under colitis conditions, ERAP1+/− mice exhibited a 70% increase in Ly6G+CD11b+ neutrophils in IELs relative to ERAP1 WT mice, indicating that partial ERAP1 deficiency may enhanced neutrophil infiltration in the gut mucosa during colitis." (PMID 40977735, 2025). "Concordantly, our study revealed a marked reduction in CD86+ cell frequency in PBLs of ERAP1+/− colitis mice, which was further diminished after sulfasalazine treatment." (PMID 40977735, 2025).
colitis (continued). "RT-qPCR analysis of splenic tissue revealed a modest reduction in Foxp3 expression in ERAP1+/− colitis mice compared with ERAP1+/− controls (p < 0.05), which persisted even after sulfasalazine treatment." (PMID 40977735, 2025). "ERAP1+/− mice with DSS-induced colitis exhibited a significant increase in circulating Ly6G+CD11b+ neutrophils compared to ERAP1+/− healthy controls, even following sulfasalazine treatment." (PMID 40977735, 2025). "Further, ERAP1+/− colitis mice showed a higher frequency of CD11c+ cells than WT colitis mice following sulfasalazine treatment." (PMID 40977735, 2025). "Hepacam2 expression was further increased in ERAP1+/− colitis mice following sulfasalazine treatment, reinforcing its potential as a biomarker for UC subtypes and ERAP1-related immune modulation." (PMID 40977735, 2025). "This study investigated the immunomodulatory role of ERAP1 in the context of DSS-induced colitis, focusing on immune cell dynamics, gene expression profiles, and therapeutic responses to sulfasalazine." (PMID 40977735, 2025). "This study elucidates the role of ERAP1 in modulating immune responses during DSS-induced colitis and its impact on sulfasalazine efficacy." (PMID 40977735, 2025). "Wild-type (WT) and ERAP1+/- mice were treated with 2.5% dextran sulfate sodium to induce colitis, followed by sulfasalazine administration." (PMID 40977735, 2025). "Atp2a1, a gene associated with increased risk of IBD, also showed a significant increase in expression in sulfasalazine-treated ERAP1+/− colitis mice compared to ERAP1+/− controls (p < 0.001)." (PMID 40977735, 2025). "In PBLs, the frequencies of CD40+ and CD80+ cells were significantly increased in DSS-treated ERAP1+/− mice (p < 0.01) and in sulfasalazine-treated ERAP1+/− colitis mice (p < 0.05) compared to ERAP1+/− healthy controls." (PMID 40977735, 2025). "In contrast, sulfasalazine-treated ERAP1+/− colitis mice exhibited a reduction in both NK1.1+ and CD8+NK1.1+ cells compared to healthy ERAP1+/− controls." (PMID 40977735, 2025). "In PBLs, ERAP1+/− colitis mice exhibited a significant increase in the frequencies of Ly6G+, CD11b+, and Ly6G+CD11b+ cells compared to ERAP1+/− healthy controls (p < 0.05)." (PMID 40977735, 2025). "We demonstrated here that loss of ERAP1 also results in excessive proinflammatory cytokine and chemokine responses during DSS-induced colitis." (PMID 35246034, 2022). "Moreover, CD8+ T cells were considerably decreased in ERAP1+/− colitis mice in contrast to WT colitis mice (p < 0.05)." (PMID 40977735, 2025). "Furthermore, under colitis conditions, ERAP1+/− mice exhibited a 64% decrease in Foxp3 expression compared with WT mice." (PMID 40977735, 2025). "Notably, CD40+ cell frequencies remained elevated in ERAP1+/− colitis mice even after sulfasalazine treatment, compared to WT colitis mice (p < 0.05)." (PMID 40977735, 2025). "Additionally, sulfasalazine treatment led to a reduction in spleen size in both WT and ERAP1+/− colitis mice compared to those treated with DSS alone." (PMID 40977735, 2025). "DSS-induced colitis model was used to investigate the role of ERAP1 in colitis development." (PMID 40977735, 2025). "Additionally, NK1.1+ cell levels were markedly lower in ERAP1+/− colitis mice compared to WT colitis mice (p < 0.05) after sulfasalazine treatment." (PMID 40977735, 2025). "Similarly, ERAP1 WT colitis mice also showed elevated levels of Ly6G+CD11b+ neutrophils compared to healthy WT controls." (PMID 40977735, 2025). "Notably, mRNA expression levels of Anxa9 (p < 0.05), Atp2a1 (p < 0.001), and Hepacam2 (p < 0.01) were all significantly upregulated in ERAP1+/− colitis mice relative to WT colitis mice after sulfasalazine treatment, indicating its potential role in colitis pathogenesis and therapeutic response." (PMID 40977735, 2025).
colitis (continued). "Notably, CD40+ and CD11c+ cells were further elevated in sulfasalazine-treated ERAP1+/− colitis mice than in WT counterparts, indicating an altered immune response and potential dysregulation in antigen presentation under conditions of ERAP1 haploinsufficiency." (PMID 40977735, 2025). "Therefore, investigating the effects of sulfasalazine in DSS-induced colitis models with partial ERAP1 expression may provide valuable insights into colitis pathogenesis and therapeutic modulation." (PMID 40977735, 2025). "CD8+ T cells were also decreased in the PBLs of ERAP1+/− colitis mice relative to WT colitis mice, and NK1.1+ cell frequencies were significantly lower in the IELs of ERAP1+/− colitis mice than WT colitis mice after sulfasalazine administration." (PMID 40977735, 2025). "Colon length, a key indicator of colitis severity, was significantly reduced in DSS-treated WT and ERAP1+/− mice compared to controls." (PMID 40977735, 2025). "In sulfasalazine-treated ERAP1+/− colitis mice, the percentages of NK1.1+ (p < 0.05) and CD8+NK1.1+ (p < 0.05) cells were reduced than those in ERAP1+/− healthy controls." (PMID 40977735, 2025). "In contrast, sulfasalazine reduced CD11c+ cell expression in WT colitis mice, suggesting a possible restorative immune effect in WT, but not in ERAP1+/− conditions." (PMID 40977735, 2025). "Sulfasalazine treatment ameliorated some of these pathological alterations in WT colitis mice but failed to improve colonic damage in ERAP1+/− mice." (PMID 40977735, 2025). "Furthermore, ERAP1+/− colitis mice exhibited higher levels of CD40+, CD80+, and CD83+ cells compared to WT colitis mice." (PMID 40977735, 2025). "Moreover, an in vivo colitis model utilizing dextran sodium sulfate (DSS) confirmed increased levels of proinflammatory cytokines and chemokines in the colon of DSS treated ERAP1−/− mice as compared to identically stimulated WT mice." (PMID 35246034, 2022). "Notably, despite the known anti-inflammatory properties of sulfasalazine, its administration failed to alleviate colitis symptoms in ERAP1+/− mice." (PMID 40977735, 2025).
enthesitis (3 papers, 2011 to 2023). Inflammation at the site of insertion of ligaments, tendons, and other fibrous structures into bone. "We observed that patients with the ERAP1 rs2287987 AA genotype more frequently presented with enthesitis (AA vs. G+, p = 0.049, OR = 4.636, 95% CI 1.101–21.24)." (PMID 35629038, 2022).
HCMV infection (3 papers, 2020 to 2023). "This review will focus on the relevance of ERAP1 SNPs within miRNA binding sites in modulating viral miRNA–mRNA interactions and the possible consequent individual susceptibility to HCMV infection." (PMID 32824160, 2020). "In this review, we focus on the relevance of 3′ untranslated region (3′UTR) ERAP1 SNPs within miRNA binding sites in modulating miRNA–mRNA interactions and the possible consequent individual susceptibility to HCMV infection." (PMID 32824160, 2020). "HCMV infection leads to the downregulation of ERAP1 mRNA through viral microRNAs miR-US4-1 and miR-UL112-5p." (PMID 36995940, 2023). "In summary, directing further investigations to the SNPs discussed here, and deepening knowledge on how 3′UTR ERAP1 variants may alter the mechanism of action of viral miRNAs, may be useful for the development of antiviral therapies or for the treatment of complications caused by HCMV infection." (PMID 32824160, 2020). "Therefore, given the known role of ERAP1 in regulating blood pressure through its involvement in the renin–angiotensin system, both SNPs should be investigated in relation to HCMV infection." (PMID 32824160, 2020). "Several of the PM proteins that were strongly upregulated during VACV infection were also upregulated at the cell surface during HCMV infection, including HSPA5, CALR and ERAP1." (PMID 35727847, 2022).
non-small cell lung carcinoma (3 papers, 2021 to 2023). A group of at least three distinct histological types of lung cancer, including non-small cell squamous cell carcinoma, adenocarcinoma, and large cell carcinoma. "Based on in silico analysis performed with the use of the TCGA database, the authors showed that in non-small cell lung cancer, a higher ERAP1 mRNA expression level in the tumor correlates with better patient survival." (PMID 37101107, 2023). "Polymorphisms of antigen-processing machinery genes were not tested so far in non-small cell lung cancer, except for our previous report on the ERAP1 gene showing highly significant associations in Chinese but not in Polish populations." (PMID 34149699, 2021).
psoriatic arthritis (3 papers, 2011 to 2019). Joint inflammation associated with psoriasis. "Recent studies have shown a CC haplotype of SNPs rs30187/rs27044 within the gene ERAP1 confers a protection effect to psoriatic arthritis (PsA)." (PMID 29715312, 2018). "In addition to MHC class I genes, endoplasmic reticulum aminopeptidase (ERAP1 and ERAP2) gene variations have been associated with psoriatic arthritis in the Romanian population." (PMID 31130981, 2019).
rheumatoid arthritis (3 papers, 2017 to 2025). A chronic, systemic autoimmune disorder characterized by inflammation in the synovial membranes and articular surfaces. "Specifically, this strategy was employed to investigate the comprehensive mechanism of total glucosides of peony (TGP) for rheumatoid arthritis (RA) treatment, pointing to ERAP1 as one of the hub TGP’s angiogenesis regulators in this chronic autoimmune disease." (PMID 40226591, 2025).
asthma (2 papers, 2014 to 2022). "Among the disease-specific genes that were induced in allergic rhinitis patients with or without asthma but not in healthy controls, there were genes (ERAP1, LAMP2) that have been shown to be involved in antigen presentation." (PMID 24475887, 2014).
cervical intraepithelial neoplasia (2 papers, 2020). "Conversely, at protein level only ERAP1 synthesis was significantly increased in HPV16-positive cell lines and in cervical intraepithelial neoplasia and cervical cancer lesions." (PMID 32183384, 2020).
glioblastoma (2 papers, 2009 to 2025). The most malignant astrocytic tumor (WHO grade IV).
HIV-1 infection (2 papers, 2020 to 2024). The type species of lentivirus and the etiologic agent of acquired immunodeficiency syndrome (AIDS). "We screened for an independent association signal for 10 ERAP1 SNPs with HIV-1 infection outcome; eight of the SNPs are the most frequent ERAP1 SNPs (with >1% frequency) reported and shown to be a risk factor for many diseases." (PMID 38980912, 2024).
Kawasaki disease (2 papers, 2021 to 2022). A rare inflammatory disease characterized by an acute febrile, systemic, self-limiting, medium-vessel vasculitis primarily affecting children. "A PEAR1 polymorphism has previously been associated with coronary artery aneurism in Kawasaki disease and ERAP1 was identified as a susceptibility locus for Kawasaki disease in a Chinese population." (PMID 34531865, 2021). "A different PEAR1 variant than the one identified in the present study has previously been associated with risk of coronary artery aneurism in Kawasaki disease, whereas ERAP1 was identified as a novel susceptibility locus for Kawasaki disease in a genome-wide association study." (PMID 34531865, 2021). "Only P5 had variants in genes (PEAR1, ERAP1) previously linked to Kawasaki disease." (PMID 34531865, 2021).
leukemia (2 papers, 2022 to 2023). A malignant (clonal) hematologic disorder, involving hematopoietic stem cells and characterized by the presence of primitive or atypical myeloid or lymphoid cells in the bone marrow and the blood. "ERAP1 is the protein target of an anti-leukemia drug, tosedostat, and NQO1 is the protein target of an anti-neurodegressive drug, vatiquinone." (PMID 36388766, 2022).
lung adenocarcinoma (2 papers, 2021 to 2023). A carcinoma that arises from the lung and is characterized by the presence of malignant glandular epithelial cells. "Our study demonstrates an overall reduction in HLA class I-presented immunopeptidome and downregulation of antigen presentation core complex (e.g., TAP1 and ERAP1/2) and immunoproteasome in osimertinib resistant lung adenocarcinoma cells." (PMID 34638461, 2021).
osteoporosis (2 papers, 2018 to 2021). A condition of reduced bone mass, with decreased cortical thickness and a decrease in the number and size of the trabeculae of cancellous bone (but normal chemical composition), resulting in increased fracture incidence. "In experiments to evaluate bone morphogenesis of the axial skeletons in ERAP1 −/− mice, the authors have found that ERAP1 −/− mice can serve as a useful model for AS to observe spinal ankyloses, osteoporosis and inflammation." (PMID 35127698, 2021). "Cross-fostered ERAP1−/− mice did not resolve spinal inflammation or reduce the severity of ankylosis and osteoporosis, downplaying the role of the intestinal microbiota in these phenotypes." (PMID 30127455, 2018).
rheumatic disease (2 papers, 2024 to 2025). "How can we explain the differences observed in our research and others on the role of ERAP1 gene in rheumatic diseases, especially RA and AS?" (PMID 39906739, 2024).
spondylitis (2 papers, 2017 to 2024). The inflammation of a vertebra. "The debate on how HLA-B27 is implicated in inflammation is also considered, together with recent and contradictory evidence on the effects of the peptide-trimming enzyme ERAP1 on B27 expression and hence susceptibility to spondylitis." (PMID 28413624, 2017). "Furthermore, evidence of the distinctive influence of ERAP2 based on HLA binding specificities in Ankylosing Spondylitis studies suggests the likelihood of different HLA alleles and/or ERAP1 and 2 haplotypes in our study and other cohorts limits the ability to replicate results with existing data." (PMID 38980912, 2024).
ankylosis (1 paper, 2018). Fixation and immobility of a joint. "Here we show that global deficiency of the ERAP1 gene caused development of spontaneous axial ankylosis, spinal inflammation, and progressive systemic osteoporosis in mice." (PMID 30127455, 2018). "Despite transfer of the aberrant microbiota derived from ERAP1−/− mice to CF WT mice, no ankylosis or significant changes in the bone density measures were observed in the latter." (PMID 30127455, 2018).
atopic dermatitis (1 paper, 2021). "The ERAP1 rs26618 affects the efficiency of a precursor peptide trimming for the HLAC*05-bound epitope, and it was displayed in a fraction of atopic dermatitis patients." (PMID 34745129, 2021).
central centrifugal cicatricial alopecia (1 paper, 2026). "Genetic studies have linked central centrifugal cicatricial alopecia (CCCA) and frontal fibrosing alopecia (FFA) to specific gene mutations, including PADI3 mutations on chromosome 1 and ERAP1/MHC class I variants on chromosome 5, respecitvely." (PMID 41362859, 2026).
channelopathy (1 paper, 2023). Channelopathies are a group of diseases caused by the dysfunction of ion channel subunits or their interacting proteins. "Other interesting gene variants in AS about Piezo2 channelopathy are the prostaglandin EP4 receptor (EP4)-coding PTGER4 gene and the endoplasmic reticulum aminopeptidase-coding ERAP1 gene." (PMID 37895134, 2023).
chronic hepatitis B (1 paper, 2022). "Here, we show that the serum level of ERAP1 in patients with chronic hepatitis B (CHB) (n = 128) was significantly higher than that of healthy controls (n = 44) (8.78 ± 1.82 vs. 3.52 ± 1.61, p < 0.001)." (PMID 35602060, 2022).
colon carcinoma (1 paper, 2018). "Interestingly, DG013A, a first generation pseudopeptide containing a phosphinic group was a potent inhibitor of ERAP1 and ERAP2 activity and was demonstrated to enhance CD8+ T-cell responses against a murine colon carcinoma cell line." (PMID 30054427, 2018).